CCAR2 (cell cycle and apoptosis regulator 2)
Diseases named in the same sentence as CCAR2 in open-access papers (continued):
Sharing a sentence is not in itself a finding about the gene and the disease.
cancer (23 papers, 2010 to 2025). A tumor composed of atypical neoplastic, often pleomorphic cells that invade other tissues. "CCAR2 is a nuclear protein and is reported to be associated with the Wnt/β-catenin signaling pathway in cancer." (PMID 37686441, 2023). "By contrast, CCAR2-deficient cancer cells grow slowly, suggesting its role as a promoter for tumor cell survival." (PMID 30609639, 2019). "Here, we demonstrate, for the first time, that CCAR2 loss inhibits the proliferation of cancer cells, but preserves the growth of normal cells." (PMID 27809307, 2016). "Collectively these results indicate that, in cancer cells, CCAR2 loss induces the accumulation of TRB3 leading to an augmented binding and inhibition of AKT." (PMID 27809307, 2016). "In particular, we demonstrate that CCAR2 loss causes a strong reduction of cancer cell proliferation associated with a significant increase of TRB3 at both transcript and protein level." (PMID 27809307, 2016). "Altogether these results suggest that CCAR2 loss negatively impacts on AKT activation only in cancer cells." (PMID 27809307, 2016). "Upregulation of CCAR2 is associated with short overall survival and relapse-free survival in various human cancers, suggesting that CCAR2 can be used as a prognostic marker for the survival of cancer patients and as a novel target for cancer therapy." (PMID 37524873, 2023). "However, CCAR2 deficiency resulted in the formation of a multilobulated nucleus in A549 and HeLa cancer cells, and IMR-90 and WI-38 normal cells." (PMID 35672287, 2022). "In addition, gene CCAR2, identified as important for all nine cancer types with B2, has been reported to be associated with the development of many cancer types." (PMID 31405076, 2019). "Finally, we tested if CCAR2 loss can increase the sensitivity of cancer cells to anti-cancer agents." (PMID 27809307, 2016). "CCAR2 also protects cancer cells from mitochondrial oxidative stress-induced apoptosis by activating the expression of mitochondrial survivin by interacting with HSP60, a prosurvival chaperone in mitochondria." (PMID 37524873, 2023). "Together, these results suggest that CCAR2 plays a crucial role in cancer progression by regulating chromatin structure and function to establish a favorable epigenetic environment for cancer-specific gene expression." (PMID 37524873, 2023). "Here, we review recent progress in understanding the dual tumor-suppressing and oncogenic roles of CCAR2 in cancer." (PMID 37524873, 2023). "With regard to cancer, the role of CCAR2 as either a tumor promoter or suppressor is still controversial." (PMID 35672287, 2022). "With regards to cancer, CCAR2 is also a research hotspot, as it plays a pleiotropic role as both tumor suppressor and tumor promoter." (PMID 36239351, 2022). "Deleted in breast cancer 1 (DBC1; also known as CCAR2) is a nuclear protein containing multifunctional domains and plays a critical role in a variety of cancers." (PMID 35913115, 2022). "Ccar2 is responsible for integrating transcript elongation with the regulation of alternative splicing, and when upregulated, it favors cancer development." (PMID 33540902, 2021). "The results also suggest that CCAR2 and Hsp60, as well as survivin, are useful therapeutic targets for cancer." (PMID 30609639, 2019). "The depletion of CCAR2 can impair the activation of the AKT pathway, which ultimately causes the inhibition of cancer cell growth." (PMID 31405076, 2019). "In summary, both CCAR2 and Hsp60 are required for expression of survivin, and both promote cancer cell survival, at least in part, by maintaining survivin expression." (PMID 30609639, 2019).
cancer (continued). "CCAR2 knockout mouse embryonic fibroblasts proliferate faster than wild-type cells, which is the opposite phenotype to that observed in cancer cell lines." (PMID 29416683, 2018). "Overall, the data suggest that CCAR2 plays a critical role in controlling both the cancer secretome and cancer progression." (PMID 29416683, 2018). "The role of CCAR2 as a tumor promoter is supported by findings that it promotes proliferation, migration, and invasion of cancer cells and suppresses cancer cell anoikis." (PMID 29416683, 2018). "Cell cycle and apoptosis regulator 2 (CCAR2) is a multifaceted protein that controls diverse cellular functions; however, its function in cancer is unclear." (PMID 29416683, 2018). "With respect to cancer growth, CCAR2 is thought to act as a tumor promoter or tumor suppressor depending on the context." (PMID 29416683, 2018). "All these data indicate that CCAR2 depletion inhibits selectively the proliferation of cancer cells, in a SIRT1 independent manner, by reducing AKT activation." (PMID 27809307, 2016). "As evidenced in the charts, CCAR2 depletion protected cancer cells from etoposide induced cell death, but increased their sensitivity to tamoxifen." (PMID 27809307, 2016). "As these differences cannot account for the growth defect detected in cancer cells, we analyzed the effect of CCAR2 silencing on cell cycle progression." (PMID 27809307, 2016). "Here, we show for the first time that CCAR2, TRB3 and AKT are linked together in a regulatory pathway that controls cancer cell proliferation and leaves unaffected the growth of non malignant cells." (PMID 27809307, 2016). "Recent reports have shown that deleted in breast cancer 1 (DBC1/CCAR2) is an indicator of poor prognosis of various human cancers." (PMID 25823848, 2015). "Altogether these results suggest that CCAR2 is required for the repair of DSBs in both normal and cancer cells and that this CCAR2 function is cell cycle and SIRT1 independent." (PMID 26158765, 2015). "Our work described Sirt1's expression related to that of Ccar2 (Cell cycle and apoptosis regulator 2, also named Deleted in breast cancer 1 or KIAA1967), a protein that directly inhibits the deacetylation activity of Sirt1." (PMID 25594010, 2014). "However, recent research, reviewed by Jeong Hoon Kim at Sungkyunkwan University, Seoul, South Korea, and co-workers, shows that CCAR2’s role in cancer is more complex than first thought." (PMID 37524873, 2023). "CCAR2 has been reported to be downregulated or upregulated and to serve as either an indicator of good or poor prognosis in various cancers, even in the same type of cancer, including breast cancer." (PMID 37524873, 2023). "CCAR2 is overexpressed by several cancers, and expression is related to prognosis." (PMID 30609639, 2019). "Taken together, the results suggest that CCAR2 may be a potential therapeutic target for inflammatory diseases and cancer." (PMID 29416683, 2018). "However, although the role of CCAR2 in the DNA damage response is well established, its function in tumor formation and cancer progression is still controversial." (PMID 27809307, 2016). "Finally, our studies suggest a model in which CCAR2 depletion in cancer cells promotes the inactivation of the AKT pathway by altering the transcription of genes coding for proteins implicated in the regulation of AKT activity, such as TRB3." (PMID 27809307, 2016). "This phenomenon suggests that cancer cells, owing to accumulated alterations during the transformation process, may become addicted to CCAR2 expression, and its ablation may establish a synthetic lethality effect." (PMID 27809307, 2016). "Alternatively, CCAR2 could interact with some transcriptional regulators and modulate their activity differently in cancer and normal cells." (PMID 27809307, 2016).
cancer (continued). "Our studies demonstrate a critical role for CCAR2 in cancer cell proliferation, where its depletion negatively impacts on their growth ability, but they also interestingly show, for the first time, that CCAR2 absence preserves the proliferation of normal cells." (PMID 27809307, 2016). "In addition, CCAR2 has been reported to be required for the antiapoptotic activity of cancer cells." (PMID 37524873, 2023). "CCAR2 has a complicated shape that allows it to perform many functions, including regulating proteins that reorganize DNA architecture to expose or hide genes, activating or deactivating them, and thereby suppressing or promoting cancer depending on the genes involved." (PMID 37524873, 2023). "Understanding CCAR2’s dual nature may help in developing new treatments for various cancers." (PMID 37524873, 2023). "CCAR2 depletion could affect the anchorage-independent growth of several types of cancer cells." (PMID 31963158, 2020). "However, further studies will be necessary to elucidate the mechanisms responsible for this differential behavior of CCAR2 in normal and cancer cells and will provide useful insights for the discovery of novel therapeutic targets for the treatment of multiple cancers." (PMID 27809307, 2016). "Therefore, we demonstrated that the inhibition of AKT activity by CCAR2 depletion in cancer cells could be, at least in part, due to the upregulation of TRB3 gene, which results in TRB3 protein accumulation and increased interaction with the AKT protein." (PMID 27809307, 2016). "However, less is known about the function of CCAR2 in tumor formation and cancer progression." (PMID 27809307, 2016). "Moreover, the involvement of CCAR2 in the repair of heterochromatic DNA breaks suggests a new role for this protein in the maintenance of chromosomal stability, which is necessary to prevent cancer formation." (PMID 26158765, 2015). "CCAR2 (cell cycle and apoptosis regulator 2; also known as DBC1, deleted in breast cancer 1) is a multifaceted protein that regulates diverse physiological and pathological conditions." (PMID 35672287, 2022). "CSNK2A1 serves cancer progression by inducing the phosphorylation of various molecules, including SIRT1, SIRT6, and CCAR2." (PMID 34359939, 2021). "In gastric cancer cells, CSNK2A1 is involved in cancer progression by stimulating proliferation and invasiveness through the phosphorylation of DBC1/CCAR2 and the PI3K-Akt-mTOR pathway." (PMID 34359939, 2021). "CCAR2, found on human chromosome 8 (8p21.3), is involved in multiple cellular processes, and like ESRP1, it has a dual role in cancer depending on the context." (PMID 31963158, 2020). "Among them, the DEPs involved in the occurrence and development of cancer are detailed in the protein cluster diagram, including MAPK14, MAPK1 and CCAR2." (PMID 32082999, 2020). "We next verified the effect of CCAR2 knock-down on AKT activation and interestingly found a correlation in all cancer cells between growth inhibition and decreased AKT phosphorylation." (PMID 27809307, 2016). "Altogether these results suggest that CCAR2 depletion reduces AKT activation and consequently GSK3β phosphorylation, finally preventing G1/S transition in cancer cells." (PMID 27809307, 2016). "Given the roles of CCAR2 in various aspects of the DDR and other cellular processes, it is no surprise that CCAR2 expression is frequently altered in cancers." (PMID 38172598, 2024). "We have shown that CCAR2 facilitates long-range chromatin interactions between distal enhancers and promoters of tumor-promoting genes such as PROX1, MACC1, and CDH2 in cancer cells, suggesting that CCAR2 activates oncogenic gene transcription by regulating chromatin architecture." (PMID 37524873, 2023).
cancer (continued). "Investigating the mechanisms responsible for this differential effect, we found that CCAR2 depletion specifically impairs the activation of AKT pathway in cancer cells, but not in normal cells, by reducing AKT phosphorylation on Ser473." (PMID 27809307, 2016). "One hypothesis is that CCAR2 depletion could lead to a synthetic lethal effect with the hyperactivation of AKT, mainly detectable in cancer cells." (PMID 27809307, 2016). "This analysis found 11 proteins immunoprecipitating with ESRP1, among which cell cycle and apoptosis regulator protein 2 (CCAR2 alias DBC1, KIAA1967) was an optimal candidate, which could partly explain how ESRP1 participated in cancer progression in CRC cells." (PMID 31963158, 2020). "Thus, it suggests that CCAR2 itself does not affect the survival of cancer patients, but CCAR2-dependent IL-8 expression does." (PMID 29416683, 2018). "However, further experiments are necessary to determine the reason why CCAR2 has this effect specifically in cancer cells and not in normal cells." (PMID 27809307, 2016). "In accordance with this hypothesis, we found that TRB3, whose gene transcription is induced by aminoacids deprivation, and which is known to inhibit AKT activation, is upregulated in cancer cells depleted of CCAR2, but not in normal cells." (PMID 27809307, 2016). "Another possibility is that CCAR2 loss, which is known to induce metabolic defects, could be more detrimental in cancer than in normal cells because of the Warburg effect and because of normal cells ability to activate AKT also in the absence of CCAR2." (PMID 27809307, 2016). "Analysis of a BJ-hTERT-CCAR2−/− clone revealed that this protein is required for efficient repair of DSBs, after genotoxic treatment and, thus, this CCAR2 function is not restricted to cancer cells." (PMID 26158765, 2015).
tumor (21 papers, 2013 to 2026). "Moreover, CCAR2-knockout mice were more susceptible to tumor development, and their disease-free survival was significantly lower than that of wild-type mice." (PMID 37524873, 2023). "In addition, the data suggest that CCAR2 deficiency fosters a pro-inflammatory tumor microenvironment." (PMID 29416683, 2018). "As expected, overall survival of the low CCAR2/high IL-8 group was shorter than that of the low CCAR2/low IL-8 and high CCAR2/low IL-8 groups, suggesting that low CCAR2 expression is associated with high IL-8 expression and contributes to create aggressive tumor microenvironment." (PMID 29416683, 2018). "CCAR2 is a cell cycle and apoptosis regulator that significantly enhances the sensitivity of tumor chemotherapy through multiple molecular mechanisms." (PMID 40765823, 2025). "CCAR2 depletion suppresses the tumorigenic and metastatic potential of CRPC cells, suggesting a tumor-promoting role for CCAR2 in the development and progression of both androgen-sensitive prostate cancer and CRPC." (PMID 37524873, 2023). "(J) EdU proliferation analysis of different tumor cells isolated from SIAH2 knockout or SIAH2/CCAR2 double-knockout xenografts." (PMID 35913115, 2022). "(F–H) Tumor images (F), tumor growth curves (G), and tumor weight (H) from mice subcutaneously injected with SIAH2 knockout or SIAH2/CCAR2 double-knockout MDA-MB-231 cells." (PMID 35913115, 2022). "(I) Immunohistochemical analysis of SIAH2 knockout and SIAH2/CCAR2 double-knockout xenograft tumor tissues with the indicated antibodies." (PMID 35913115, 2022). "This implies that CCAR2 and Hsp60 play a role in survival of tumor cells, possibly by upregulating survivin." (PMID 30609639, 2019). "CCAR2 knock-out mice develop spontaneous tumors, indicating a potential role of CCAR2 as a tumor suppressor." (PMID 30609639, 2019). "Considering that IL-8 is a chemokine fertilizing tumor microenvironment, CCAR2 is one of critical factors to be tightly regulated." (PMID 29416683, 2018). "Here, we show that CCAR2 modulates expression and secretion of IL-8 by tumor cells under oxidative conditions." (PMID 29416683, 2018). "The tumor-promoting role of CCAR2 is further supported by recent meta-analyses." (PMID 37524873, 2023). "In this review, we discuss recent advances in our understanding of the role and mechanism of CCAR2 as a key coregulator of TFs and epigenetic modifiers, paying special attention given to the dual role of CCAR2 as a tumor suppressor and tumor promoter during tumorigenesis." (PMID 37524873, 2023). "Additionally, knockout of SIAH2 promoted apoptosis and reduced cell migration and tumor proliferation, whereas double knockout of CCAR2 and SIAH2 partially rescued cell proliferation and tumorigenesis." (PMID 35913115, 2022). "In addition, although the previous studies show that CCAR2 regulates tumor cell proliferation, migration, and invasion, the mediators of CCAR2 functions have not been identified." (PMID 29416683, 2018). "Therefore, although the exact role of CCAR2 as a tumor promoter or tumor suppressor in humans is unclear, CCAR2 plays an intimate part in tumor development and progression." (PMID 29416683, 2018). "CCAR2 knockout mice spontaneously develop tumors of the liver and lung, teratomas, and lymphomas." (PMID 29416683, 2018). "The role of CCAR2 in the oxidative tumor microenvironment is unclear." (PMID 29416683, 2018). "Although the link between CCAR2 and tumor cells has been studied, the role of CCAR2 in the tumor microenvironment remains unclear." (PMID 29416683, 2018). "CCAR2 may also exert tumor-suppressive effects by regulating transcription." (PMID 38172598, 2024).
tumor (continued). "Thus, CCAR2 is a critical factor that fine-tunes the tumor microenvironment." (PMID 29416683, 2018). "KLLN (killin), a tumor suppressor that enhances SUV39H1 HMT activity, promotes H3K9me3 deposition at the pericentric region by interfering with the inhibitory effect of CCAR2 on SUV39H118." (PMID 37524873, 2023). "SIAH2 knockout inhibited tumor cell proliferation and migration, which could be rescued by double knockout of SIAH2/CCAR2." (PMID 35913115, 2022).
adenocarcinoma (1 paper, 2016). A common cancer characterized by the presence of malignant glandular cells. "The clustering also highlighted a set of proteins that was almost solely present in control tissue of adenocarcinoma patients, including FANCJ, CCAR2, AGRIN, and LAMC1." (PMID 26930711, 2016).
CCAR2 also shares sentences with these, for which no sentence is quoted: osteosarcoma (3 papers); ovarian carcinoma (3); lung squamous cell carcinoma (2); non-small cell lung carcinoma (2); Obesity (2); cardiovascular disease (1); cervical tumor (1); clear cell renal cell carcinoma (1); colorectal cancer (1); diabetes (1); diffuse large B-cell lymphoma (1); dyslipidemia (1); esophageal cancer (1); esophageal squamous cell carcinoma (1); Hypertension (1); lung carcinoma (1); metabolic disorders (1); soft tissue sarcoma (1); thyroid (1); triple-negative breast carcinoma (1).